EGFR (epidermal growth factor receptor)
Diseases named in the same sentence as EGFR in open-access papers (continued):
Sharing a sentence is not in itself a finding about the gene and the disease.
tumor (continued). "n = 29/141Observed association between EGFR amplification and release of CTCs.Common genomic abnormalities in CTCs and GBM tumours." (PMID 38481938, 2024). "This suggests that EGFR plays a crucial role in mediating the inhibitory effects of kaempferol on glycolysis in tumor cells." (PMID 38730663, 2024). "Combined with the results of previous results in this paper, it can be concluded that the C1 SRSF7+ MCs and tumor cells crosstalk through the AREG-EGFR/AREG-(EGFR+ERBB2) signal pathway, thereby exerting a tumor-promoting effect." (PMID 39430754, 2024). "The downstream EGFR signaling pathway usually promotes cell proliferation, angiogenesis, tumor metastasis and invasion and reduction of apoptosis." (PMID 39075515, 2024). "Overexpression of mutant EGFR variant III (EGFRvIII), present in about 30% of nGBM, has been recognized as a tumor-specific, oncogenic epitope able to mediate increased cellular growth, invasion and angiogenesis, and resistance to chemoradiation in GBM cells." (PMID 38339353, 2024). "GPER1 promotes tumor progression mainly by interacting with carcinogenic signaling pathways, such as the EGFR/ERK1/2 pathway, the PI3K/AKT/mTOR signaling pathway, and the MAPK/ERK signaling pathway." (PMID 38383297, 2024). "First, we improved their tumor-homing abilities by increasing their affinity for EGFR-overexpressing cells by attaching cetuximab to their surface using the Z domain expressed on their CPs." (PMID 38673914, 2024). "Eligible criteria included isocitrate dehydrogenase (IDH) wild-type GBM after previous radiotherapy and evidence of EGFR amplification confirmed by fluorescence in situ hybridization (FISH) on any previous tumor sample." (PMID 38727262, 2024). "EGFR abnormality, which is driven by amplification and/or EGFRvIII mutation, is a prognostic marker in GBM and correlates with higher tumor malignancy, poorer prognosis, and shorter survival time." (PMID 38474286, 2024). "siRNA and ASO technologies can target genes like KRAS and EGFR, effectively inhibiting tumor cell proliferation and metastasis, and significantly enhancing treatment outcomes." (PMID 39857631, 2024). "After oral osimertinib administration, significant suppression of EGFR Y1068 phosphorylation was observed at 6 hours in IHC-stained tumor tissues." (PMID 39041204, 2024). "The PI3K/AKT/mTOR pathway involves receptor tyrosine kinases (RTKs) such as EGFR and a tumour suppressor protein, PTEN, which acts as an antagonist of PI3K, contributing to the downregulation of this pathway and inhibiting cell proliferation." (PMID 38674436, 2024). "Because of the high expression rate and role that EGFR plays in alteration of tumor development, progression, angiogenesis, invasion, and survival, EGFR is an exciting potential target for immunotherapy." (PMID 39364321, 2024). "Both mRNAs promoted EGFR-specific tumor cell lysis and PD-L1 -dependent costimulatory activity in vitro, respectively, and exhibited favorable pharmacokinetic properties in vivo." (PMID 39835115, 2024). "In this study, 6-MP combined with gefitinib was used to study the effect on tumor growth of EGFR-mutant LUAD." (PMID 39343971, 2024). "Here, we developed a protein engineering strategy to generate EGFR-specific CARs with improved tumor specificity." (PMID 38492569, 2024). "Given its pivotal role in eliciting various downstream signaling cascades crucial for cell proliferation, cell cycle progression, cell survival, and tumor growth, EGFR represents a prominent target for therapeutic intervention." (PMID 39668367, 2024). "Nevertheless, CRC tumours are typically heterogenous, consisting of multiple genetically different clones, some of which carry wild type forms of these oncogenes, even within tumours that are resistant to EGFR‐targeting chemotherapies." (PMID 38887984, 2024). "Cetuximab binds with high specificity to the extracellular domain III of the epidermal growth factor receptor (EGFR), which is overexpressed in these tumor cells." (PMID 39339258, 2024).
tumor (continued). "Modelling studies were used to visualize the binding model of six derivatives within the Erlotinib binding site in the EGFR enzyme, which is upregulated in most tumor cells to defend itself for survival." (PMID 39496648, 2024). "In order to evaluate the anti-tumor efficacy of improved CAR-T cells, researchers co-cultured them with GBM organoid containing multiple EGFR mutations." (PMID 38443969, 2024). "This study enrolled EGFR-mutated NSCLC patients who had received ≥1 EGFR TKI(s), and 48% of patients experienced tumor regression at doses of 400 mg/day or higher with BLU-945 monotherapy." (PMID 39061985, 2024). "For example, osimertinib, an SMI known as an epidermal growth factor receptor (EGFR) tyrosine kinase inhibitor (TKI) demonstrates the potential to induce ICD in non-small cell lung cancer (NSCLC) tumor cells through the exposure and release of CRT." (PMID 38774648, 2024). "EGFR is overexpressed in more than 60% of all NSCLCs and regulates several cellular processes relevant for tumor progression." (PMID 38177097, 2024). "Human homologs of seven in absentia (SIAH) expressed in the residual tumor was proved to be a new biomarker to forecast the tumor relapse by leveraging the activation or inactivation of EGFR/K‐RAS/SIAH pathway recently." (PMID 38348939, 2024). "IHC staining showed that EGFR and PD-L1 were both highly expressed in the tumor area in both CAL27-Fluc and HSC3 mouse models." (PMID 39183296, 2024). "Nevertheless, previous studies have shown that plasma detection of RAS mutations has a high level of concordance with tissue biopsy results and a similar predictive level for benefit of anti-EGFR treatment as standard tumor tissue testing." (PMID 38347302, 2024). "Multi-kinase inhibitors achieve anti-tumor effects by inhibiting the epidermal growth factor receptor (EGFR) signaling pathway." (PMID 39777333, 2024). "In contrast, TKIs inhibit kinase activity and autophosphorylation by competitively binding the ATP binding site of the EGFR tyrosine kinase domain and blocking EGFR-mediated signal transduction, thus inhibiting tumor cell proliferation." (PMID 39777265, 2024). "The EGFR group was as follows: normal=1±0.08; benign=1.12±0.12; precancerous=1.15±0.11; and tumor=1.22±0.10." (PMID 38633382, 2024). "The combination treatment was supposed to inhibit tumor growth not only by directly blocking EGFR signaling, but also by consequently restoring antitumor immune response such as PD-L1 downregulation in EGFR-mutant cells." (PMID 39090096, 2024). "The epidermal growth factor receptor (EGFR) belongs to tyrosine kinase family and is responsible for tumor growth and metastasis; therefore, it represents a potential therapeutic target." (PMID 39478959, 2024). "EGFR, a tyrosine kinase receptor, plays a pivotal role in the growth regulation of both normal cells and malignant tumor cells." (PMID 39399463, 2024). "Their research highlighted tumor heterogeneity and the activation of survival pathways, particularly mutations in RAS and the epidermal growth factor receptor (EGFR), as key contributors to resistance against targeted therapies." (PMID 38673727, 2024). "Treatment of resistance to anti-EGFR therapies remains a challenge, since genomic alterations of resistance are multiple and coexist within one same tumor." (PMID 38711991, 2024). "Fourthly, a spectrum of RTKs/nRTKs, comprising PDGFR, VEGFR, FGFR-1, EGFR, AXL, Src, and c-Kit, have been implicated in inducing TNBC cell invasion and migration, and enhancing exit from the primary tumor microenvironment." (PMID 39668367, 2024). "The practicability of FOM for tumor discrimination was analyzed using vital tissue labeling with anti-EGFR AY13 or mixed anti-EpCAM 9C4/anti-CD31 WM59 mAbs." (PMID 38883274, 2024). "The epidermal growth factor receptor (EGFR) is frequently overexpressed in a variety of human epithelial tumors, and its aberrant activation plays a pivotal role in promoting tumor growth, invasion, and metastasis." (PMID 39766327, 2024).
tumor (continued). "Among them, GINS3 was characterized by high tumor purity, immune-desert, activation of EGFR and ephrin receptors, chromosomal instability, fewer KRAS mutations, SMOC1 methylation, immunotherapeutic resistance, and high sensitivity to cetuximab and bevacizumab." (PMID 38429655, 2024). "In cancer, EGFR contributes to tumor progression by promoting invasion and metastasis and stimulating tumor angiogenesis." (PMID 38699644, 2024). "EGFR signaling is an important pathway dysregulated in CRC to promote tumor progression and metastasis." (PMID 40727266, 2024). "Critically, EGFR contributes to the accelerated proliferation of tumor cells and promotes angiogenesis, rendering it an optimal target for targeted NSCLC therapy." (PMID 38389925, 2024). "Our findings indicated that these nanoparticles displayed pH-responsive cytotoxicity, precise EGFR targeting, efficient tumor penetration, successful endosomal escape, and accurate nuclear and cytoplasmic localization." (PMID 39482441, 2024). "The resulting ER cells exhibited a dramatic increase in erlotinib resistance, a decreased EGFR protein level, and enhanced tumor growth, suggesting a robust mechanism bypassing EGFR inhibition." (PMID 39897079, 2024). "Upon uptake of this nanosystem by EGFR-positive breast cancer cells, endogenous ROS in the tumor region trigger the disassembly of NPs by cleaving thione bonds and releasing doxorubicin (DOX) and Pc molecules." (PMID 38399272, 2024). "By analysing the landscape of miRNAs in this context, they found that miR‐182‐5p, miR‐96‐5p, and miR‐183‐5p were expressed at a significantly higher level in EGFR‐amp tumours." (PMID 39148319, 2024). "Validating new biomarkers for tumor diagnosis and therapy is crucial, as current targets such as EGFR, HER2, and VEGFR2 are insufficient for treating various solid tumors and dealing with emerging drug resistance." (PMID 38888519, 2024). "In tumor cells expressing both Trop2 and EGFR, DM001 exhibited comparable internalization and tumor-killing efficacy to that of its parent anti-Trop2 and anti-EGFR mAbs." (PMID 38948057, 2024). "Despite carrying a small molar fraction (1.65%) of the SNS-032 inhibitor, the ADC restricted EGFR-expressing spheroid and cell line/patient-derived xenograft tumor growth." (PMID 38772416, 2024). "When combined with short bursts of RT, this approachimproved the targeting efficiency of NPs, resulting in enhanced downregulationof EGFR and PD-L1 and increased tumor growth inhibition." (PMID 38861272, 2024). "Tumors with strong in more than 10% of the tumor cells were considered EGFR positive, which was observed in only 18 cases (21.7%)." (PMID 39405290, 2024). "The application of this engager resulted in in vitro and ex vivo augmented activation of patient PBMC NK cells and lysis of EGFR-expressing tumor cell lines and metastatic colorectal patient-derived cancer cells." (PMID 39339180, 2024). "The development of acquired BRAF V600E has been reported to render tumor insensitivity to EGFR-TKIs treatment, indicating potential clinical benefits of EGFR and BARF co-inhibition in cases with dual mutations." (PMID 39135785, 2024). "PAN is a monoclonal antibody that acts against the epidermal growth factor receptor (EGFR), which presents, especially, dermatological adverse reactions, such as less severe and frequent skin rashes, compared to cytostatic treatments." (PMID 39594802, 2024). "The role of the epidermal growth factor receptor (EGFR) in tumor progression and survival is often underplayed." (PMID 38474312, 2024). "miR-34a was also demonstrated to directly target TF YY1, which results in EGFR overexpression and GB tumor growth." (PMID 38473710, 2024). "Epidermal growth factor receptor (EGFR) was wild‐type, and the tumor cells expressed programmed death‐ligand 1 (PD‐L1) at a rate of <1%." (PMID 39290250, 2024).
tumor (continued). "The greater energy reflected the lower internal heterogeneity of the tumor and lower malignant degree of the tumor, correspondingly, the higher expression of EGFR protein, which was in contradiction with our expectations." (PMID 38396128, 2024). "Earlier research indicated a strong link between EGFR and tumor cell growth, prompting us to investigate EGFR and its phosphorylated form in CRC cells treated with HDCA." (PMID 39834394, 2024). "After genetic modification of human primary CD8+ T‐cell‐derived exosomes, they were impregnated with IL‐2 and cetuximab (CTX), an anti‐EGFR antibody, which has the potential to augment tumor cytotoxicity and refine cancer targeting." (PMID 39611045, 2024). "Currently, anti-Axl and anti-EGFR therapies (mAbs and TKIs) have demonstrated significant clinical benefits for the treatment of patient with NPC; however, acquired resistance to Axl or EGFR in tumor cells is a major obstacle in NPC management." (PMID 39594573, 2024). "All three tumor cell lines express high levels of EGFR and SKOV3-A2 cells also expresses high levels of Her2." (PMID 37945970, 2024). "Immunoblotting results from these resected tumor tissues revealed high B7-H3 and EGFR expression in the LoVoOXR group." (PMID 38370387, 2024). "Downstream dimerization and activation of EGFR initiate the processes like cells proliferation, preclusion of apoptosis, angiogenesis induced by tumour, invasion activation and metastatic growth, which can lead to cancer." (PMID 39434198, 2024). "In mice, combined EGCG with tamoxifen leads to a decrease in tumor volume by 71% and tumor weight by 80% by inhibiting mTOR and EGFR expression." (PMID 39725830, 2024). "Playing a key role in mediating cell growth factor signaling, overexpression of EGFR signaling widely promotes tumor progression and leads to promotion of proliferation and inhibition of apoptosis." (PMID 39430754, 2024). "In contrast to the cancer-promoting epidermal growth factor receptor (EGFR), EphA2 exerts tumor-suppressive effects through the ligand-dependent tyrosine phosphorylation (pY588) of specific tyrosine residues in the presence of its ligand." (PMID 39766211, 2024). "Research has shown that EGFR is highly expressed in various tumor cells, particularly in TNBC, where its overexpression is closely associated with aggressive features such as high invasiveness, increased risk of distant metastasis, and poor prognosis." (PMID 39399463, 2024). "In the scRNA sequencing data, GSE159115, EGFR is likewise upregulated in tumor cells compared with benign epithelial cells." (PMID 39333870, 2024). "Multiregion sequencing of the primary tumor and metastatic sites revealed differences in the genomic profiling, including oncogene amplifications such as EGFR, ERBB2, MET and PIK3CA." (PMID 38611014, 2024). "In this context, the combination of inhibitors of AURKA and EGFR has been explored and shown promising activity in several tumor types." (PMID 38639476, 2024). "In our discussion, we will compare the MET family’s role in pro-tumor metabolism with one of the most well-characterized RTKs, EGFR." (PMID 39062731, 2024). "In LC with activated epidermal growth factor receptor (EGFR) mutation, overexpression of immunoglobulin-like transcript (ILT) 4 in tumor cells induces recruitment of TAMs and M2-like polarization." (PMID 39144141, 2024). "Preclinical pharmacodynamic studies demonstrated the ability of gefitinib to effectively block EGFR signaling and inhibit tumor growth in animal models." (PMID 38611728, 2024). "Erlotinib is an EGFR tyrosine kinase inhibitor that inhibits tumor cell proliferation and survival by blocking the EGFR signaling pathway." (PMID 39741907, 2024). "It has been knowm that metabolic reprogramming is an important hallmark of malignant tumors, and purine metabolism is a key metabolic pathway for tumor progression and drug resistance, but its relationship with the EGFR-mutant LUAD is unclear." (PMID 39343971, 2024).
tumor (continued). "We found that EGFR was directly related to tumor differentiation, such that its expression increased with increasing grade of the tumor, and this was found to be statistically highly significant among the three grades (p = 0.000) of OSCCs." (PMID 39050298, 2024). "GALNT10 and GALNT18 are members of the GalNAc polypeptide N‐acetyl‐galactosaminyltransferases, which catalyse O‐linked glycosylation of mucin and can promote EGFR O‐glycosylation and subsequent AKT phosphorylation, leading to tumour proliferation." (PMID 38279874, 2024). "We used three human tumor cell lines (A431, A549, and SK-BR-3) expressing different EGFR levels on their surface, ranging from ∼104 – 5 × 105 receptors per cell." (PMID 38492569, 2024). "•Epidermal growth factor receptor (EGFR) is identified as a potential driver of an immune cold tumour microenvironment." (PMID 38744099, 2024). "Specifically, the combination of an epidermal growth factor receptor (EGFR) antibody with irinotecan was endorsed as a strategic intervention for cases where the tumor expresses EGFR." (PMID 38844562, 2024). "Although the use of EGFR‐TKIs has shown benefits for patients with advanced NSCLC and EGFR mutations, it is inevitable that tumor cells will develop drug resistance, thus leading to disease progression." (PMID 39631794, 2024). "The observation that expression of FUCA1 inhibits the EGFR pathway, implicated in promoting cancer, again supports the potential role of FUCA1 as a tumor suppressor." (PMID 39123480, 2024). "In contrast, although PD-L1 expression reflects the presence of tumor-infiltrating lymphocytes (TILs), there are reports that PD-L1 expression is a prognostic marker for resectable NSCLC harboring an EGFR mutation." (PMID 39280252, 2024). "Single cell RNA (scRNA) sequencing, bulk RNA sequencing, multiplexed immunofluorescence (mIF) and flow cytometry were performed on pretreatment and post-resistant tumor samples from EGFR-mutant NSCLC patients received third-generation EGFR-TKIs." (PMID 39638994, 2024). "In univariate analysis, patients with N2-3, EGFR mutation-positive, LYM%≤20, and elevated tumor markers(P<0.05) were more likely to develop brain metastases." (PMID 38605303, 2024). "Including a human skin graft to their NSG mouse xenograft model, they showed that EGFR CAR-Ts both controlled tumor but also infiltrated the grafted human tissue." (PMID 39606234, 2024). "Chemotherapy regimens containing oxaliplatin or irinotecan, along with anti-EGFR for tumors with wild-type RAS/BRAF or anti-VEGF for tumors with RAS/BRAF mutations, were successful in enhancing the rate of tumor removal and improving overall survival." (PMID 38834909, 2024). "For example, sialyltransferase inhibition was effective in reducing tumor cell loads in xenografted models using SCID or CD89 transgenic SCID mice treated with anti-EGFR IgG1, -IgG2 or -IgA2 antibodies." (PMID 39659795, 2024). "The current investigation focused on exploring the underlying mechanism of aberrant glycosylation of SEMA7A in HNSCC and its role in tumor progression, EGFR-targeted therapy, immunotherapy, and splicing regulation." (PMID 38548747, 2024). "By using microarray data of non-small cell lung cancer (NSCLC) tumor tissues and matched normal tissues of 42 NSCLC patients, the genetic and clinical associations between PTK2, EGFR, and TLRs were analyzed in NSCLC patients." (PMID 38816856, 2024). "Lysine demethylase 3A (KDM3A) regulates anti-tumor immunity through epidermal growth factor receptor (EGFR) expression in cancer cells." (PMID 38817612, 2024). "Tumour-sidedness is a variable that has been incorporated into clinical practice, with left-sided location favoring EGFR mAb use compared to right-sided tumours." (PMID 38402342, 2024). "In a phase II study, SI-B001 demonstrated anti-tumor activity with manageable toxicity when combined with chemotherapy in locally advanced or metastatic EGFR/ALK wild-type NSCLC in the second-line setting." (PMID 39337530, 2024).